BRAF (B-Raf proto-oncogene, serine/threonine kinase)
Diseases named in the same sentence as BRAF in open-access papers (continued):
Sharing a sentence is not in itself a finding about the gene and the disease.
melanoma (continued). "In the melanoma arm of a phase 1b trial of patients with advanced solid tumors, the combination of cobimetinib and atezolizumab resulted in an ORR of 41% in a mixed BRAF mutant/wild-type cohort." (PMID 33810078, 2021). "Small molecular inhibitors, effecting on KRAS, EGFR, ALK in lung cancer 11, BRAF and MEK in melanoma cells 63, elicit concurrent GSDME-mediated PCD." (PMID 34335940, 2021). "We also report results demonstrating that methiothepin increases the effectiveness of the BRAF inhibitor vemurafenib and of the MEK inhibitor trametinib against resistant BRAFV600E melanoma cells." (PMID 33810240, 2021). "In human melanoma, HDAC8 was also shown to induce a resistance to BRAF inhibition through targeting c-JUN." (PMID 34064422, 2021). "Recent efforts to develop improved targeted therapies for melanoma have mainly focused on the BRAF-mutant subtype, leaving a paucity of treatment options for patients with NF1-mutant melanomas." (PMID 34331013, 2021). "Inhibition of the mitogen-activated protein kinases (MAPK) signalling pathway through the combined use of BRAF and MEK inhibitors is a well-established approach for treating BRAF-mutant melanoma." (PMID 34590600, 2021). "The observed radio-sensitization in BRAF- and NRAS-mutant melanoma cells lines treated with TRT and MEKi combination will need, in the future, to be assessed by in vivo studies using human BRAF- and NRAS-mutant melanoma xenografts." (PMID 33804655, 2021). "A multicenter retrospective cohort study reported on patients with melanoma BM treated with SRS and BRAF inhibitors." (PMID 34359583, 2021). "BRAF is more commonly mutated in younger patients with more nevi and sun exposure and those with superficial-spreading melanoma (SSM) (up to 50%) and is now targeted with BRAF + MEK small molecular inhibitors as a front-line treatment." (PMID 34698235, 2021). "miR-579-3p also controls melanoma progression and its sensitivity to target therapy by targeting the 3′UTR of two oncoproteins: BRAF and an E3 ubiquitin protein ligase, MDM2." (PMID 34288804, 2021). "Preclinical data show that adding a BRAF- to a MEK-inhibitor inhibits ERK-phosphorylation and cell growth and induces apoptosis in NRAS mutant melanoma models by inducing endoplasmic reticulum stress." (PMID 33921947, 2021). "Since the last decade, two different treatment concepts are available for targeted therapy, BRAF ± MEK inhibition, and immune checkpoint blockade, which confirmed a survival benefit for advanced melanoma patients." (PMID 33993415, 2021). "The use of phenformin has shown not only to enhance the therapeutic effect of BRAF inhibitors but also to inhibit MDSC activity and increase the efficacy of anti-PD1 in melanoma." (PMID 34073463, 2021). "The study cohort consisted of 19 advanced melanoma patients (11 with Stage III and 8 with Stage IV), among which 15 underwent BRAF testing, with 5 patients harboring BRAF-mutants and 10 patients showing a WT BRAF mutant status." (PMID 33574842, 2021). "Considering that several ETS factors are direct targets of MAPK pathway signaling, an examination of YK-4-279 treatment for both BRAF and NRAS driven melanomas has significance." (PMID 35008307, 2021). "The emergence of advanced BRAF/MEK targeted therapy and immunotherapy have resulted in significant improvement in survival rates among advanced-stage melanoma patients." (PMID 33824801, 2021). "It has been established that inhibition of the MAPK pathway with BRAF and MEK inhibitors induces de-differentiation of BRAF mutant human melanoma cells." (PMID 33520112, 2021). "We previously found that decreased Ptch1 expression in MeWo and A375 melanoma cells using silencing RNA against Ptch1 strongly inhibited the efflux of doxorubicin, indicating that Ptch1 is involved in doxorubicin efflux in melanoma cells carrying or not the BRAF mutation." (PMID 33810240, 2021).
melanoma (continued). "Malignant melanoma is characterized by both genetic and molecular alterations that activate phosphoinositide 3-kinase (PI3K), and RAS/BRAF pathways." (PMID 37305163, 2021). "It has been indicated that the IGF-1R expression in melanomas is regulated by the surrounding stromal cells as well as the PTEN and BRAF status." (PMID 34830178, 2021). "Recently, with the advent of BRAF/MEK inhibitors and immunologic therapies, the unmasking of intracranial metastatic disease from melanoma in the setting of systemic disease control has also been reported." (PMID 33824801, 2021). "The oncogene BRAF acts through MEK and the cGMP-specific phosphodiesterase PDE5A, which enhances melanoma cell invasion by increasing cGMP and upregulating cytosolic Ca2+, contractility." (PMID 33718200, 2021). "To date, BRAF and MEK inhibitors remain the only approved targeted therapy with a high level of evidence in BRAFV600E/K mutant melanomas." (PMID 34831002, 2021). "Small-molecule BRAF and MEK inhibitors (vemurafenib, dabrafenib, and trametinib) have revolutionized treatment and have improved the progression-free survival of melanoma patients with advanced-stage and metastatic melanoma." (PMID 33498201, 2021). "Taken together, these data suggest that the combination of ECCA and a BRAF inhibitor targets two separate pathways (apoptosis and proliferation) to enhance the growth inhibition of BRAFV600E expressing melanoma cells." (PMID 34103468, 2021). "Here, we focus on BRAF and MEK inhibitors, and their use in treating the most prevalent form of melanoma, BRAFV600 melanoma." (PMID 34025662, 2021). "Pharmacological inhibition of BRAF with vemurafenib and MEK with PD0325901 markedly reduced basal phospho-ERK (pERK) in melanoma cells while increasing SOX2, and this induction was specific to the inhibitor treatment as it was time dependent." (PMID 33613844, 2021). "Melanomas with NRAS-mutant cells and BRAF-mutant cells have greater resistance to BRAF inhibitors, likely due to selection of NRAS mutant populations." (PMID 35008286, 2021). "LXH-254, an ATP-competitive inhibitor of BRAF and CRAF, is used in multiple clinical trials for patients with NSCLC or melanoma." (PMID 34607583, 2021). "Vemurafenib is a BRAF inhibitor that interrupts BRAF/MEK signaling in the BRAF/MEK/ERK pathway and was first developed for the treatment of melanoma." (PMID 33567635, 2021). "When the original melanoma cells with wild-type PTEN were changed to inactivated PTEN status, they became resistant to BRAF inhibition; they had similarly upregulated PERK, confirming that PERK upregulation in resistant melanoma is dependent on PTEN." (PMID 34282258, 2021). "Therefore, a BRAF mutation alone, as frequently found in melanocytic nevi, is not sufficient for melanoma development but might rather be complemented by additional mutations." (PMID 34576054, 2021). "Nevertheless, these BRAF mutations are commonly present in benign nevi; thus, mutation of BRAF alone is not sufficient to initiate melanomagenesis; therefore, additional oncogenic alterations are required to drive melanocyte transformation and melanoma development." (PMID 34282258, 2021). "It is unlikely that the FDA-approved BRAF-mutant-specific inhibitors will be beneficial against BRAF-wild-type, NF1-mutant melanomas." (PMID 34331013, 2021). "However, a first clinical test of this concept demonstrated that continuous dosing was superior to intermittent dosing of combination BRAF/MEK inhibitor therapy for advanced melanoma, questioning whether this concept from mouse models may translate to the human disease setting." (PMID 33924486, 2021). "Although targeted therapies that center on this pathway (e.g., BRAF and MEK1/2 inhibitors) prolong patients’ survival in unresectable melanoma, most patients relapse within 6–7 months." (PMID 33810045, 2021).
melanoma (continued). "Indeed, our results demonstrate that the binding of methiothepin to Ptch1 increases the cytotoxicity of five different chemotherapeutic drugs (doxorubicin, cisplatin, oxaliplatin, vemurafenib and trametinib) against various melanoma cell lines carrying or not a BRAF mutation." (PMID 33810240, 2021). "Targeting MAPK pathway using a combination of BRAF and MEK inhibitors elicits a 70% response rate in patients with BRAF-mutant melanoma." (PMID 34304249, 2021). "These include drugs targeting the mitogen activated protein-kinase (MAPK) pathway, namely, BRAF and MEK inhibitors, in patients with BRAF mutant melanoma (i.e., approximately 50% of patients with cutaneous melanoma)." (PMID 34073463, 2021). "Finally, it has been suggested that pharmacological inhibition of histone H3K9 demethylase, either alone or in combination with MAPKi, and co-targeting of EZH2 together with one of its regulators, NFATc2, may benefit the treatment of resistant BRAF V600E melanomas." (PMID 34440824, 2021). "This provides further evidence that, in melanoma, EZH2 mediates miR-129-5p expression downstream of constitutive active BRAF signaling." (PMID 34063443, 2021). "Murine B16-OVA, SM1 and BRAF mutant D4M3.A and YUMM1.7 melanoma cell lines are other examples that have been used to test in vivo the therapeutic effect of drug candidates." (PMID 34831311, 2021). "Prior systemic treatment had been administered in 2/20 melanoma patients (anti-CTLA-4 and BRAF-targeted therapy)." (PMID 34071888, 2021). "The ability of CRAF to induce the same metabolic changes seen with BRAF over-expression, even after BRAF inhibition, along with its unique role in influencing mitochondria morphology, makes CRAF an important target for research on melanoma metabolism." (PMID 34831420, 2021). "The first trial is currently enrolling both NRAS mutant cutaneous melanomas and KRAS or BRAF mutant non-small cell lung cancers progressed after standard of care therapy, while the second one is focused on pre-treated BRAF or NRAS mutant melanomas." (PMID 34071228, 2021). "The CDKN2A/CDK4/6 pathway has a role in the G1–S transition in the cell cycle, which is dysregulated in BRAF and NRAS mutant melanomas." (PMID 34831002, 2021). "We know from data of melanoma patients that combining BRAF and MEK inhibitors is better than BRAF-directed monotherapy, due to resistance of the tumor cells." (PMID 33799327, 2021). "To evaluate the safety and efficacy of triple combination of PD-1/PD-L1, BRAF, and MEK inhibition in patients diagnosed with stage III-IV melanoma, we performed a systematic review and meta-analysis of randomized controlled trials (RCTs)." (PMID 34195094, 2021). "A number of pre-clinical studies have shown promising results from combining BRAF or BRAF and MEK inhibition with ICB for the treatment of melanoma." (PMID 34025662, 2021). "Combined BRAF (vemurafenib) and DUB inhibition effectively suppressed BRAF mutant melanoma in vitro colony growth (2D and 3D) and in vivo tumor growth, suggesting that combining these agents can block adaptive resistance mechanisms such as SOX2 induction." (PMID 33613844, 2021). "It should be noted that BRAF class I/II/III mutants are present in 65.9%, 11.4%, and 9.5% of melanoma patients, respectively." (PMID 33917428, 2021). "In these studies, combined BRAF and CDK4/6 inhibition overcomes resistance to BRAF inhibitor monotherapy in vitro and in vivo in pre-clinical xenograft models of human melanoma." (PMID 34025662, 2021). "Consequently, JIB extract can be potentially utilized as an anti-melanoma agent and adjuvant treatment in the future and this study might provide a new therapeutic strategy for patients who do not have BRAF mutations and cannot receive immunotherapy." (PMID 33390784, 2021). "Viewed together, these observations demonstrate that BRAF- and MEK-targeted therapies induce metabolic plasticity, and this limits the response to these therapies in melanoma." (PMID 34830962, 2021).
melanoma (continued). "The final trial reported that has investigated the benefit of the addition of an anti-PD-L1/PD-1 antibody to BRAF and MEK inhibitors in BRAFV600 mutant melanomas is IMSPIRE-150." (PMID 33827575, 2021). "Our results provide evidence that mTOR inhibitor in combination with BRAF and MEK inhibitors blocked the growth of CR melanoma cells primarily due to cell cycle arrest." (PMID 34304249, 2021). "It has been documented that small molecule inhibitors (vemurafenib and dabrafenib) of BRAF V600–mutant induce tumor regression, and combination of BRAF and MEK inhibitors can improve survival rate of melanoma patients." (PMID 34044811, 2021). "In a prospective study involving 80 patients with melanoma BM, SRS combined with BRAF inhibitors was found to increase OS (median OS 11.2 vs. 4.5 months) compared to SRS alone." (PMID 34359583, 2021). "Determining the optimal individual treatment after disease progression upon initial BRAF ± MEKi therapy might therefore be another important issue for clinical trials, as it may contribute to a better outcome and even lead to durable tumor responses in melanoma patients." (PMID 34065877, 2021). "Here we used the mitogen-activated protein kinase (MAPK) pathway inhibitors vemurafenib (PLX4032) (mutant BRAF inhibitor, mBRAFi) and trametinib (MEK inhibitor, MEKi) as these are frontline therapeutics in the management of melanoma in the clinic." (PMID 34070332, 2021). "Maertens and colleagues found that combined suppression of BRAF/MEK together with entinostat resulted in additional downregulation of NHEJ related genes, including XRCC4, XRCC5, XRCC6, PNKP and PARP3, and reduced melanoma cell survival." (PMID 33800547, 2021). "BRAF, NRAS, CDKN2A, CDK4, and other RTKs like ROS1, ALK, MET, RET, and NTRK1 are also other candidates for melanoma development to be considered." (PMID 34630850, 2021). "We examined Usp9x and SOX2 expression levels in a panel of BRAF- and NRAS-mutant melanoma cell lines." (PMID 33613844, 2021). "Accordingly, targeted therapies for melanoma, aiming BRAFV600E/K-expressing tumours, have involved the use of the BRAF inhibitor, vemurafenib, which was approved by the Food and Drug Administration (FDA) for unresectable or stage IV melanomas." (PMID 33916029, 2021). "Similarly, BRAF mutations in mucosal melanomas mainly consist of non-canonical non-V600 mutations and are similar to those observed in lung adenocarcinomas for both the location of mutated codons and the preferred amino acid substitutions (mostly prevalence of D594G, G469A, and K601E)." (PMID 35008570, 2021). "Together, our results show that sma-10/LRIG is a conserved regulator of RTK signaling, add to our understanding of LRIG1 in melanoma and identifies recombinant LRIG1 as a potential therapeutic against BRAF inhibitor-resistant melanoma." (PMID 33947959, 2021). "In this work, we showed using 3D in vitro tumor models, an additive efficiency of combining [131I]ICF01012-TRT and MAPK/ERK inhibitors in BRAF- and NRAS-mutant melanoma cells." (PMID 33804655, 2021). "This is followed by ERK signalling activation that altogether leads to the resistance of melanoma cells to PLX4720, which can be circumvented by the inhibition of BRAF and FAK." (PMID 33803675, 2021). "Targeted therapies, like combinations of BRAF inhibitors (Dabrafenib) and MEK inhibitors (vemurafenib) are also frequently used on BRAFV600E mutant melanomas." (PMID 33968718, 2021). "BRAF- or KRAS-driven colorectal cancer and BRAF-driven melanoma exhibit increased glycolysis, and inhibition of BRAFV600E suppressed the levels of glycolysis in BRAF-driven melanoma." (PMID 34298710, 2021). "The use of dabrafenib (BRAF inhibitor) and trametinib (MEK inhibitor), two FDA approved drugs to treat patients with BRAFV600E melanoma, is limited in the clinic due to the development of resistance." (PMID 34831014, 2021).
melanoma (continued). "The development of therapeutic strategies targeting BRAF and MEK and the introduction of immunotherapy represented a big challenge in the treatment of melanoma." (PMID 33670365, 2021). "Using genome-scale analyses, melanoma has been classified into four distinct groups based on their NRAS, BRAF, and NF1 status: NRAS-mutant, BRAF-mutant, NF1-mutant, and triple-negative (NRAS/BRAF/NF1 mutant) melanoma." (PMID 33766731, 2021). "In melanoma, activation of TGF-β signaling directly upregulates the expression of EGFR and platelet-derived growth factor receptor-β, which leads to BRAF inhibitor resistance." (PMID 34247571, 2021). "The most common genetic subtypes of human melanoma, neuroblastoma RAS viral oncogene homolog (NRAS)- and v-Raf murine sarcoma viral oncogene homolog B (BRAF)-mutant, are enriched in different anatomical locations." (PMID 34210801, 2021). "Concurrent targeting of both CDK4/6 and MEK resulted in enhanced cell death in both BRAF- and NRAS-mutant melanoma." (PMID 33806615, 2021). "These genomic subtypes include BRAF-mutant melanoma (50%), NRAS, KRAS and HRAS-mutant melanoma (25%), NF1-mutant melanomas (15%) and triple wild-type melanomas (10%)." (PMID 34572747, 2021). "Nelfinavir improves the approach of targeted melanoma therapy by sensitizing BRAF and NRAS mutant melanomas to MAPK pathway inhibitors." (PMID 33918792, 2021). "A second cluster of fitness genes related to melanoma consisted of components of the MAPK signaling pathway, such as BRAF and MAPK1." (PMID 32767816, 2021). "Several BRAF-driven cancers, including advanced BRAFV600E/K-driven melanoma, non-small-cell lung carcinoma, and thyroid cancer, are currently treated using first-line inhibitor combinations of BRAFV600E plus MEK1/2." (PMID 34298710, 2021). "Here, we show that combining TRT with MEKi can overcome such activation by reducing ERK phosphorylation in BRAF- and NRAS-mutant melanoma." (PMID 33804655, 2021). "Moreover, it was reported that BRAFV600E-driven melanoma cells were less sensitive to mTORC1 inhibitor-mediated autophagy induction (e.g., via rapamycin), suggesting a greater therapeutic benefit for combined inhibition of PI3K→AKT→mTOR signaling plus autophagy in non-BRAF-mutated melanoma cells." (PMID 34298710, 2021). "In preclinical melanoma models, Hirata and colleagues showed that tumor cells present in areas of high stromal density display rapid reactivation of MAPK signaling after BRAF inhibitor treatment." (PMID 34071428, 2021). "Based on the importance of metabolism in targeted therapy response in melanoma, we characterise how CDK4/6 inhibition reprograms metabolism in BRAFV600 melanoma, alone and in combination with BRAF and MEK inhibitors." (PMID 33572972, 2021). "Although vemurafenib has been approved as a treatment regimen for melanoma, it shows resistance to both class II and class III BRAF mutants." (PMID 33917428, 2021). "As melanoma is characterized by activation of MAPK signaling due to mutations in BRAF, NRAS, NF1 and KIT genes, this suggests that further hyperactivation of MAPK signaling through loss of inhibitors of this signaling pathway may be deleterious to melanoma cells." (PMID 32767816, 2021). "The combination of BRAF and MEK inhibition that tackle this resistance mechanism has become the standard of treatment for melanoma patients." (PMID 34804979, 2021). "Three BRAF inhibitors - vemurafenib, dabrafenib and encorafenib — are now approved for treatment of BRAFV600E/K mutant melanoma." (PMID 33367512, 2021). "The use of BRAF and MEK inhibitors for patients with BRAF-mutant melanoma is limited as patients relapse on treatment as quickly as 6 months due to acquired resistance." (PMID 34831014, 2021). "Rapid progress in BRAF and MEK targeted therapy (TT) and immunotherapy (IT) has led to significant improvements in objective response and survival rates in advanced melanoma patients." (PMID 34064013, 2021).